PARP16 (poly(ADP-ribose) polymerase family member 16)
Description:
Intracellular mono-ADP-ribosyltransferase that plays a role in different processes, such as protein translation and unfolded protein response (UPR), through the mono-ADP-ribosylation of proteins involved in those processes. Acts as an inhibitor of protein translation by catalyzing mono-ADP-ribosylation of ribosomal subunits, such as RPL14 and RPS6, thereby inhibiting polysome assembly and mRNA loading. Mono-ADP-ribosylation of ribosomal subunits is promoted by NMNAT2. Involved in the unfolded protein response (UPR) by ADP-ribosylating and activating EIF2AK3 and ERN1, two important UPR effectors. May also mediate mono-ADP-ribosylation of karyopherin KPNB1 a nuclear import factor. May not modify proteins on arginine or cysteine residues compared to other mono-ADP-ribosyltransferases.
Synonyms: ARTD15; C15orf30; FLJ20509; FLJ25281; pART15
Tractability: Small molecule: a structure with a bound ligand is known; a high-quality ligand is known. Antibody: UniProt predicts a signal peptide or a membrane-spanning region. PROTAC: ubiquitination databases record sites on it; its protein half-life has been measured; a small molecule that binds it is known.
Target class: Enzyme; Transferase
Gene: Protein-coding gene on chromosome 15 (65,234,460 to 65,300,618, reverse strand). Ensembl gene ENSG00000138617.
Subcellular location: Endoplasmic reticulum membrane
Pathways (Reactome):
Disease: Maturation of nucleoprotein
Metabolism: Nicotinate metabolism
Gene Ontology:
Molecular function: kinase binding; NAD+ poly-ADP-ribosyltransferase activity; NAD+-protein mono-ADP-ribosyltransferase activity; NAD+-protein-aspartate ADP-ribosyltransferase activity; NAD+-protein-glutamate ADP-ribosyltransferase activity; NAD+-protein-lysine ADP-ribosyltransferase activity; protein binding; protein serine/threonine kinase activator activity
Biological process: endoplasmic reticulum unfolded protein response; IRE1-mediated unfolded protein response; negative regulation of cytoplasmic translation; protein auto-ADP-ribosylation; nicotinate metabolic process; viral protein processing
Cellular component: endoplasmic reticulum; endoplasmic reticulum membrane; endoplasmic reticulum tubular network; membrane; nuclear envelope; cytosol
Genetic constraint (gnomAD): Loss-of-function variants: 31 observed, 35.3 expected, observed/expected ratio (o/e) 0.88, 90% interval 0.66 to 1.18. The upper end of that interval is the gene's LOEUF score, 1.18, which puts it in group 5 of 6, group 1 being the genes least tolerant of losing a copy. Missense variants: 423 observed, 410.21 expected, observed/expected ratio (o/e) 1.03, 90% interval 0.95 to 1.12. Synonymous variants: 161 observed, 172.84 expected, observed/expected ratio (o/e) 0.93, 90% interval 0.82 to 1.06.
Homologues: Orthologues: chimpanzee PARP16 (100% identical), macaque PARP16 (99% identical), pig PARP16 (95% identical), rabbit PARP16 (93% identical), dog PARP16 (92% identical), guinea pig PARP16 (92% identical), mouse Parp16 (90% identical), rat Parp16 (89% identical), tropical clawed frog parp16 (63% identical), zebrafish parp16 (61% identical). Paralogues in human: PARP6 (25% identical), PARP8 (25% identical).
Diseases named in the same sentence as PARP16 in open-access papers:
PARP16 is named in the same sentence as 16 diseases in open-access papers, as found by Europe PMC text mining. Sharing a sentence is not in itself a finding about the gene and the disease. The quoted sentences say what the papers report.
viral infection (4 papers, 2021 to 2025). "Or are there specific triggers that activate specific ARTs, such as possibly viral infection activating the interferon-responsive ARTs, high levels of unfolded proteins activating PARP16, or translational shutdown activating the stress granule-associated ARTs." (PMID 36368907, 2023). "Cells are highly sensitive to ER membrane stress when PARP16 expression is downregulated, which suggests that PARP16 may be an important inhibitory target for the treatment of cancer, viral infections, and inflammation." (PMID 35652091, 2022). "When knockdown of PARP16 expression, cells are highly sensitive to ER stress, resulting in increased cell death, suggesting that PARP16 could be an attractive therapeutic inhibition target for cancers, viral infections, and inflammations." (PMID 34367175, 2021).
ovarian carcinoma (3 papers, 2024 to 2025). A malignant neoplasm originating from the surface ovarian epithelium. "In ovarian cancer cells, PARP16 uses NAD+ produced by the cytosolic NAD+ synthase NMNAT-2 to MARylate RPS6 and RPL24." (PMID 39760726, 2025). "Lastly, studies on ovarian cancer cells have uncovered a central role of PARP16 in cell survival." (PMID 40741921, 2025). "Moreover, we showed that PARP16, a tail-anchored endoplasmic reticulum-associated protein, is a MART that MARylates RPS6 and RPL24 in ovarian cancer cells to control the loading of mRNAs on ribosomes and their translation." (PMID 39760726, 2025). "Current studies are also focused on developing inhibitors for the PARP monoenzymes that are key therapeutic targets for ovarian cancers such as PARP7 and PARP16." (PMID 39272943, 2024). "Similar to PARP16, MARylation of key cytosolic proteins by PARP7 has been found to regulate the biology of ovarian cancer cells." (PMID 39272943, 2024).
lung carcinoma (2 papers, 2024 to 2025). "Our data demonstrated that PARP16 plays a critical role in CYB5R3-induced lung cancer cell death by increasing ADP-ribosylation of PERK and IRE1α." (PMID 38253797, 2024).
cardiac hypertrophy (1 paper, 2025). "PARP16 deficiency alleviates cardiac dysfunction, attenuates transverse aortic constriction‐induced cardiac hypertrophy/fibrosis, and reduces phenylephrine‐induced cardiomyocyte hypertrophic responses." (PMID 40904702, 2025).
hepatocellular carcinoma (1 paper, 2019). A malignant tumor that arises from hepatocytes. "ER stress-induced apoptosis, PERK and eIF2α phosphorylation by EGCG are suppressed in PARP16-deficient hepatocellular carcinoma QGY-7703 cells, so EGCG mediates apoptosis through ER stress, which is dependent on PARP16." (PMID 31719837, 2019).
lung adenocarcinoma (1 paper, 2025). A carcinoma that arises from the lung and is characterized by the presence of malignant glandular epithelial cells. "In summary, while PARP inhibition is a powerful radiosensitization strategy in lung adenocarcinoma, its success depends on understanding the interconnected roles of senescence, mitochondrial dysfunction, p21 signaling, and underexplored family members such as PARP16." (PMID 41296412, 2025).
Parkinson disease (1 paper, 2025). A progressive degenerative disorder of the central nervous system characterized by loss of dopamine producing neurons in the substantia nigra and the presence of Lewy bodies in the substantia nigra and locus coeruleus. "This study provides the first molecular insight into how CCNE1 exerts neuroprotective effects through the regulation of the ferroptosis key protein PARP16, offering a novel perspective for Parkinson's disease mechanism research." (PMID 41319014, 2025).
small cell lung carcinoma (1 paper, 2023). Small cell lung cancer (SCLC) is a highly aggressive malignant neoplasm, accounting for 10-15% of lung cancer cases, characterized byrapid growth, and early metastasis. "A growing number of studies have identified PARP16 as a potential therapeutic target, such as a unique anticancer target for small cell lung cancer and other tumors, but the development of inhibitors against PARP16 is lagging behind." (PMID 37219631, 2023).
cancer (8 papers, 2017 to 2025). A tumor composed of atypical neoplastic, often pleomorphic cells that invade other tissues. "Below, we discuss examples of MARylating PARPs – namely PARP3, PARP6, PARP7, PARP9–12, PARP14 and PARP16 – that have been linked to cancer progression and survival." (PMID 40741921, 2025). "Upon the depletion of PARP16, ovarian cells showed reduced proliferation and increased protein-specific translation, revealing how PARP16 can potentiate cancer cell homeostasis through MARylation, resulting in a honing of protein synthesis." (PMID 37508568, 2023). "With the aim to analyze the contribution of NAD+ signaling in cancer cells, this study has revealed that PARP16 supports the ADPr of ribosomal protein utilizing NAD+ synthesized in the cytoplasm by NAMNT-2, whose protein level is upregulated here." (PMID 35327636, 2022). "PARP16 has been identified as a potent novel target for cancer therapeutics when inhibited in conjunction with PARP1." (PMID 35096828, 2021). "Further investigation of PARP16 inhibitors is required to explore the utility of their use as a cancer therapeutic." (PMID 35096828, 2021). "Since these data suggest a strong correlation between UPR functionality and PARP16 activity, it would be tempting to propose a role for PARP16 in ER-stress-induced inflammation via NF-κB signaling in cancer." (PMID 34725336, 2021). "For example, silencing PARP16 in vitro reduced cancer cell survival when cells were treated with the PARP1 inhibitor Olaparib and the WEE1 inhibitor adavosertib." (PMID 35096828, 2021). "Notably, this study proposes a novel therapeutic treatment based on NAMNT-2 depletion or PARP16 inhibition relying on the strategical approach to target the NAD+ availability in cancer cells, thereby affecting the downstream NAD+-consuming enzymatic pathways." (PMID 35327636, 2022). "Due to the critical role of PARP16 in the cellular stress response, it has been speculated that PARP16 maybe an efficient cancer target." (PMID 35096828, 2021). "This raises the possibility that the off-target inhibitory effects of talazoparib on PARP16 may contribute to its potency as a selective cancer therapeutic and may support targeting PARP16 as an anti-cancer therapy." (PMID 35096828, 2021). "Moreover, EGCG suppressed the ER stress-induced phosphorylation of PERK and the transcription of unfolded protein response-related genes, leading to dramatically increase of cancer cells apoptosis under ER stress conditions, which was dependent on PARP16." (PMID 28698806, 2017). "In support of this observation, inhibition of PARP16 results in the suppression of ER-stress-induced PERK phosphorylation and increases cancer cell apoptosis under untreated and ER-stress-induced conditions." (PMID 34725336, 2021). "EGCG suppressed the activity of PARP16, then blocked the ER stress-induced UPR signaling and increased the apoptosis of cancer cells." (PMID 28698806, 2017). "Finally, we demonstrated that epigallocatechin-3-gallate (EGCG) was a potential inhibitor of PARP16, which suppressed the ER stress-induced phosphorylation of PERK and the transcription of UPR-related genes, leading to a dramatical increase of the cancer cells apoptosis under ER stress conditions." (PMID 28698806, 2017).
cardiovascular diseases (2 papers, 2020 to 2023). "Furthermore, PARP16 mainly expressed in neonatal rat cardiomyocytes (NRCMs) but not the cardiac fibroblasts in the hearts of 1–2 days of SD rats, suggesting that PARP16 may play an underlying role in cardiovascular diseases." (PMID 37219631, 2023). "Replicative senescence induces vascular cell growth arrest and loss of vascular homeostasis, contributing to the initiation and progression of cardiovascular diseases, we further examined the dynamic expression changes of PARP16 in replicative senescence of RAEC." (PMID 33144524, 2020). "However, PARP16 is the only PARP family member to be located on the endoplasmic reticulum and its role in cardiovascular diseases remains to be clarified." (PMID 37219631, 2023).
infection (2 papers, 2018 to 2023). The state of being infected such as from the introduction of a foreign agent such as serum, vaccine, antigenic substance or organism. "In addition, among 46 TRP32 target genes previously found to be differentially expressed during infection, 8 are also TRP47 targets, including CAP1, CMC1, HLX, ING1, MTFR2, NAT10, PARP16, and POLDIP3." (PMID 30408047, 2018).
tumor (2 papers, 2024 to 2025). "PARP14 and PARP16 inhibitors: The effect of inhibiting PARP14 on metabolic reprogramming phenomena in tumor models in response to energy stress." (PMID 41463260, 2025).
PARP16 also shares sentences with these, for which no sentence is quoted: Alzheimer disease (2 papers); cognitive decline (1); heart failure (1); lentivirus infection (1).